RUNX1 (RUNX family transcription factor 1)
Diseases named in the same sentence as RUNX1 in open-access papers (continued):
Sharing a sentence is not in itself a finding about the gene and the disease.
breast cancer (continued). "Co-expression of RUNX1 or RUNX3 significantly suppressed modulate YAP-mediated oncogenic phenotypes, and inhibited breast cancer progression." (PMID 36092942, 2022). "Interestingly, RUNX1 could act both as an oncogene and a tumor suppressor in breast cancer." (PMID 36429115, 2022). "We also found EGFR, MYCN, and MYC in brain cancers;39,40BCL2, MYC, and the loci of IGH translocations in lymph-nodes cancer;41–43CDK12 in breast cancer; CCND1 in liver cancer; and RUNX1, GATA6, and PDE4D in esophageal cancer." (PMID 36163358, 2022). "Through TIMER analysis, we found a positive correlation between RUNX1 gene copy number and the infiltration of B cells, CD8+T cells, CD4+T cells, macrophages, neutrophils, and dendritic cells in breast cancer." (PMID 34485309, 2021). "RUNX1 and RUNX3 preserve against YAP-induced shorter survival outcomes, stemness, and EMT in breast cancer." (PMID 34126594, 2021). "Other gene knockouts (RUNX1, CDH1, and ARID1B) have similar effect, consistent with their reported tumor-suppressor roles in breast cancer or other cancer types." (PMID 31980032, 2020). "Here, we demonstrate that PAK4 modulate the regulation of RUNX1 and that the nuclear PAK4 involving in ERα-positive breast cancer-induced osteolytic bone destruction." (PMID 32549768, 2020). "RUNX1 was recently shown to regulate lncRNAs NEAT1 and MALAT1, which have critical roles in the onset and progression of breast cancer." (PMID 32655837, 2020). "In breast cancer cells, the binding of RUNXOR lncRNA trigger CpG island DNA demethylation and activate the expression of RUNX1." (PMID 32746865, 2020). "For example, PVT1 acts as a competitive endogenous RNA that forms a tight network with protein-coding mRNAs, such as CDH1, TP73, TP31, RUNX1, and RUNX via microRNA-200, thereby regulating breast cancer progression." (PMID 32992461, 2020). "In luminal-type breast cancer cell lines (MCF7, T47D, BT474, and ZR751), RUNX1 levels were almost undetectable and CBFB levels were lower than in triple negative and basal-like types of breast cancer cell lines." (PMID 31061501, 2019). "Binding of hnRNPK and CBFB to RUNX1 mRNA was also detected in several other breast cancer cell lines, indicating that binding of hnRNPK and CBFB to RUNX1 mRNA is a general mechanism." (PMID 31061501, 2019). "The novel interplay between YAP, RUNX1 and RUNX3 and its significance in breast cancer progression can serve as a prognostic tool to predict cancer recurrence." (PMID 29581836, 2018). "To assess for the clinical significance of RUNX3 and RUNX1 mediated suppression of YAP-mediated oncogenic function, we analyzed available expression dataset of breast cancer patients." (PMID 29581836, 2018). "Hotspots were also identified at GNAS, RUNX1, and MDM2, all recognised as breast cancer genes, even if less frequent." (PMID 30252041, 2018). "Out of the three RUNX proteins, RUNX1 and RUNX3 have been recently identified as novel tumor suppressors in breast cancer." (PMID 29581836, 2018). "Although RUNX1 has been extensively studied as an oncogene as RUNX1-ETO fusion protein in blood cancers, RUNX1's function in breast cancer progression is context dependent." (PMID 29581836, 2018). "From the study, it is imperative that RUNX3 and RUNX1 regulate YAP-mediated pro-oncogenic phenotypes and YAP-RUNX1-RUNX3 axis has direct implications in breast cancer progression." (PMID 29581836, 2018). "Here, we identify RUNX1 and RUNX3 as novel negative regulators of oncogenic function of YAP in the context of breast cancer." (PMID 29581836, 2018).
breast cancer (continued). "Despite this emergent role of RUNX1 and RUNX3 as tumor suppressors in breast cancer, the mechanistic details regarding how they exert their tumor suppressor function in breast cancer is yet to be understood." (PMID 29581836, 2018). "Compared to the high level of Runx1 in normal-like basal MCF10A control cells, Runx1 mRNA and protein were significantly decreased in all breast cancer cell lines tested, but less so in the triple negative MDA-MB-231 cells." (PMID 28407681, 2017). "To mechanistically address if decreased Runx1 and EMT are coupled in breast cancer, we used a well-known method to induce EMT in mammary cells, by adding TGFβ to MCF10A cells." (PMID 28407681, 2017). "Treating ER+ breast cancer cells with 17β-estradiol promotes EMT and also decreases Runx1 expression." (PMID 28407681, 2017). "Our studies demonstrate a clear reduction of endogenous Runx1 in two cell models (MCF7 and MCF10AT1) of breast cancer." (PMID 28407681, 2017). "Based on these results, we conclude that Runx1 is preventing EMT in both normal mammary cells (MCF10A) and breast cancer cells (MCF7), consistent with its function in maintaining an epithelial phenotype." (PMID 28407681, 2017). "Interestingly, Ferrari and colleagues have shown using multivariate analysis that high expression of RUNX1 correlates with poor prognosis in triple negative human breast cancer and strongly suggest that Runx1 could be used as an independent prognostic marker in this subgroup of human breast cancer." (PMID 26735887, 2016). "We then investigated the potential role of Runx1 in the regulation of Rspo3 gene expression, in the LM3 cell line, which was derived from a spontaneous BALB/c mouse mammary tumor." (PMID 26735887, 2016). "Here, we demonstrate that RUNX1 antagonizes oestrogen-mediated inhibition of AXIN1 expression, shedding light on its breast cancer suppression role." (PMID 26916619, 2016). "RUNX1, a common partner of CBFB in hematopoietic cells, was, also, deleted in some breast cancer patients." (PMID 26561834, 2015). "Another example relevant for breast cancer is the hsa-miR-17-5p/EREG pair of miRNA and predicted target gene that putatively form FFLs with E2F1, EGR2, FOXJ2 and RUNX1." (PMID 17971223, 2007). "The involvement of RUNX1 and TCF7 in NK cell maturation has been well-documented, and TCF7 expression has been inversely correlated with lymphocyte exhaustion in human breast cancer." (PMID 40443661, 2025). "In contrast, many breast cancers—particularly aggressive subtypes—exhibit reduced or absent RUNX1 expression." (PMID 41218079, 2025). "In addition, opposing roles have recently been suggested for RUNX1 and RUNX2 in controlling the EMT of breast cancer stem cells." (PMID 38630262, 2024). "We used a real-time transcriptional activity assay known as TRACER (TRanscriptional Activity CELL aRray) to measure the dynamic activity of six transcription factors involved in EMT signaling specific for breast cancer (TWIST1, SNAIL, HIF1a, RUNX1, RUNX2, and NOTCH1)." (PMID 38398186, 2024). "This is also supported by data from the METABRIC study, where 14% of primary breast cancer samples were found to harbor alterations in CBFB, while 11%, 5% and 4% of patient samples possessed various categories of genetic alterations in RUNX1, RUNX2 and RUNX3, respectively." (PMID 36831308, 2023). "Here we show for the first time that the AR is a direct positive regulator of RUNX1 gene expression in AR+-TNBC and that RUNX1 transcriptional activity is involved in the CSC-like phenotype and chemoresistance, contributing to tumor progression in this aggressive breast cancer subtype." (PMID 36766786, 2023). "While AR-mediated activation of RUNX1 has previously been reported in prostate cancer cells, evidence for the AR directly binding to the RUNX1 promoter/gene body is limited in that context and has not been demonstrated in breast cancer." (PMID 36766786, 2023).
breast cancer (continued). "Furthermore, YAP/RUNX1 complex induces the transcription of HDAC2 to induce chemoresistance and stemness in breast cancer cells." (PMID 35494005, 2022). "In breast cancer, the expression of RUNX2 was higher than that of RUNX1 and RUNX3." (PMID 35534547, 2022). "FOXA1, together with EP300 and RUNX1, regulates the expression of E-cadherin, and is expressed in luminal, but absent in triple-negative and basal-like breast cancers." (PMID 33417085, 2021). "Furthermore, we analyzed the relationship between the expression of RUNX1 and the infiltration of six types of immune cells in BRCA-basal, BRCA-HER2, and BRCA-luminal breast cancer subtypes." (PMID 34485309, 2021). "RUNX1 directly regulates E-cadherin, and rescues TGFβ-induced EMT phenotype in breast cancer cells." (PMID 32498288, 2020). "We noted a significant reduction of RUNX1 in the luminal-type but not the triple negative type breast cancer cells compared to normal cells while the reduction of CBFB was modest." (PMID 31061501, 2019). "Five further patients (5 of 83; 6% of cohort) were found to harbor pathogenic variants in genes lacking a firm association with breast cancer susceptibility to date (i.e., Fanconi pathway genes, RECQ family genes, CDKN2A/p14ARF, and RUNX1)." (PMID 30086788, 2018). "In turn, depletion of Runx1 represses the expression of estrogen receptor α, suggesting a negative feedback loop in progression of ER+ breast cancer." (PMID 28407681, 2017). "Interestingly, module 5 (with Mucins) is mutually exclusive with many known breast cancer drivers including PIK3CA, MAP3K1, and RUNX1." (PMID 29023534, 2017). "Both RUNX1 and RUNX3 have tumor suppressor roles in breast cancers, while RUNX2 is tumor-promoting." (PMID 28412963, 2017). "Furthermore, we demonstrate that Runx1 is able to actively promote oncogene Rspo3 and prevent GJA1 gene expression in mammary tumor cell lines." (PMID 26735887, 2016). "AXIN1 mRNA significantly correlated with the RUNX1 inhibitory index in ER+ but not in the ER− breast cancer types." (PMID 26916619, 2016). "If further studies can establish if RUNX1 overexpression and STAT3 activation are conserved in human breast cancer, and in TNBC in particular, this could pave the way for new treatment options based on the use of STAT3 inhibitors." (PMID 24967588, 2014). "It is intriguing that even though RUNX1 was expressed in most breast cancer cell lines and the majority of patients regardless of hormonal status, it was only in the hormone-negative patients that RUNX1 expression correlated with patient outcome." (PMID 24967588, 2014). "RUNX1 is the predominant RUNX family member expressed in human breast epithelial cells and there is a growing body of evidence suggesting its possible role as a breast cancer suppressor." (PMID 25033876, 2014). "Recent studies have highlighted a novel link for RUNX1 with breast cancer but to date no direct assessment of RUNX1 protein has been carried out." (PMID 24967588, 2014). "Significantly, RUNX1 expression was not detectable in normal hMEC-TERT but was expressed in all breast cancer cell lines tested with the exception of BT-549." (PMID 24967588, 2014).
breast cancer (continued). "These authors extrapolated their findings by applying multiplex immunofluorescent staining to show that RUNX1 was expressed in human breast cancer fibroblasts but not in normal breast tissue, while a RUNX1-stromal signature could stratify patients." (PMID 36831308, 2023). "In addition, RUNX1 and RUNX3 may inhibit the YAP-regulated epithelial-mesenchymal transition process and improve breast cancer outcome." (PMID 34485309, 2021). "Interestingly, we found that the RUNX1 promoter methylation level was significantly lower in breast cancer tissues than in normal tissues, regardless of stage, subclass, or histological type." (PMID 34485309, 2021). "In breast cancer, overexpression of lncRNA RUNXOR alters the spatial chromatin structure of the RUNX1 gene, the interaction between the promoters and enhancers, as well as methylation modifications of histones, to regulate the different transcripts of RUNX1 expression levels." (PMID 33168103, 2020). "Indeed, previous studies have shown that RUNX1 suppresses development of ER+ luminal breast cancer but it is not known how CBFβ contributes in this context." (PMID 32005976, 2020). "Given the recent discovery of RUNX1 and RUNX3 as tumor suppressors in the context of breast cancer and their known interaction with oncogene-YAP, we investigated whether YAP-RUNX interaction plays any role in molecular pathogenesis of breast cancer." (PMID 29581836, 2018). "However, molecular basis of tumor suppressor function of RUNX1 and RUNX3 in breast cancer is largely unknown." (PMID 29581836, 2018). "Given that RUNX1 and RUNX3 interact with YAP and co-regulate transcription, we investigated whether RUNX1-RUNX3 interaction with YAP has biological significance in the context of breast cancer." (PMID 29581836, 2018). "This antagonistic activity of RUNX1 and RUNX3 towards oncogenic function of YAP identified in mammary epithelial cells as well as in breast cancer expression profiles gives a novel mechanistic insight into oncogene–tumor suppressor interplay in the context of breast cancer progression." (PMID 29581836, 2018). "For instance, recurrent mutation of RUNX1 was observed in breast cancer, suggesting absence of RUNX1 may promote breast cancer development." (PMID 27007162, 2016). "Furthermore, expression of neither c-Myc, CCND1, nor LEF1 differed in TCGA breast cancer tumours with wild-type versus mutant RUNX1." (PMID 26916619, 2016). "For instance, the most strongly associated TF with the AP-1 motif in kidney cancer is RUNX1, while in breast cancer it is FOXA1, suggesting that many of the AP-1 motif-containing sites may require AP-1 dependent de-repression along with positive RUNX1/FOXA activation." (PMID 25994056, 2015). "Four estrogen-responsive element (ERE) half sites and two runt-related transcription factor 1 (RUNX1) binding sites were detected bioinformatically in region A1 and possibly participate in the estrogen-driven downregulation of MB transcription in breast cancer cells." (PMID 26559958, 2015). "However, certain studies have also reached the opposite conclusion, finding that the absence of RUNX1 expression in breast cancer is associated with activation of the TGF-β and WNT signaling pathways, and that a low RUNX1 expression level suggests a poor prognosis in breast cancer." (PMID 38430423, 2024). "Thus, wehypothesized that RUNX1, together with CBFβ, might play a key role in mammaryepithelial cell (MEC) lineage determination as a master regulatory TF and that the lossof this normal function might contribute to breast cancer development." (PMID 25415051, 2014). "Five genes (MMP3, CDKN1A, RUNX1, TIMP2, CCND1) are common in cervical, ovarian, endometrial cancers, but not in breast cancer." (PMID 31205821, 2019).
myelodysplastic syndrome (81 papers, 2010 to 2026). A clonal hematopoietic disorder characterized by dysplasia and ineffective hematopoiesis in one or more of the hematopoietic cell lines. "Although the role of RUNX1 in normal myelopoiesis and its germline alterations resulting in predisposition to familial myelodysplastic neoplasm/AML disorders is well known, recent studies illuminate the critical role that RUNX1 plays in T-ALL cell development." (PMID 40925926, 2025). "characterized the first inherited leukemia syndrome by recognizing that germline RUNX1 variants lead to lifelong thrombocytopenia and an increased risk of myelodysplastic syndrome (MDS) and acute leukemia (AL)." (PMID 37904876, 2023). "In a study by Haferlach and colleagues, the RUNX1 gene was mutated in around 10% of patients with myelodysplastic syndrome." (PMID 32013121, 2020). "Mutations in RUNX1 are also considered to be initiating event for onset of various sporadic hematological malignancies such as myelodysplastic syndrome or chronic myelomonocytic leukemia." (PMID 26745853, 2016). "Point mutations and deletions of RUNX1 are frequently found in patients with myelodysplastic syndrome (MDS), chronic myelomonocytic leukemia (CMML) and FAB M0 AML." (PMID 27542261, 2016). "Constitutional alterations in RUNX1 predispose individuals to thrombocytopenia and hematological malignancies, mainly myelodysplastic syndrome and AML, but also T-ALL." (PMID 26102509, 2015). "RUNX1 encodes a DNA binding subunit of the core-binding transcription factors and is frequently mutated in acute leukemia, therapy-related leukemia, myelodysplastic syndrome, and chronic myelomonocytic leukemia." (PMID 22145044, 2011). "This retrospective single-center study evaluated six pediatric patients with myelodysplastic syndromes or acute leukemias harboring RUNX1 variants, integrating clinical, cytogenetic, and targeted next-generation sequencing data, with germline status confirmed using non-hematopoietic tissues." (PMID 42278335, 2026). "RUNX1 and hepcidin were observed in erythro-megakaryocytes and in platelets, suggesting a myeloid origin, and impairments of these proteins could cause myelodysplastic syndromes (MDS) and premature ageing of erythroid cells." (PMID 34209847, 2021). "RUNX1 mutations occurs in 40% of myelodysplastic syndromes (MDS)." (PMID 26384344, 2015). "At age 69 the patient was diagnosed with myelodysplastic syndrome (MDS) due to a secondary RUNX1 (Runt-Related Transcription Factor 1) mutation in a CH clone." (PMID 37573441, 2023). "Patients with Myelodysplastic Syndrome (MDS) carrying RUNX1 mutations have a higher risk and shorter latency for progression to AML10." (PMID 32572036, 2020). "In addition, point mutations in AML1/RUNX1 were observed at a high frequency in myelodysplastic syndrome (MDS)/AML cases in radiation-exposed residents near the Semipalatinsk Nuclear Test Site as compared with MDS/AMLs from unexposed individuals." (PMID 41007286, 2025). "ASXL1 is an epigenetic regulator and the mutations in ASXL1 gene often coexist with RUNX1 and SETBP1 mutations in myelodysplastic syndromes (MDS) and AML14." (PMID 38129572, 2023). "Intragenic mutations of the RUNX1 gene were preliminary reported in MDS, secondary and therapy-related AML, radiation exposed myelodysplastic syndrome (MDS) and AML." (PMID 37188777, 2023). "Mutations and translocations in the RUNX1 gene are frequently seen in acute myeloid leukaemia (AML), myelodysplastic syndromes (MDS) and other forms of haematological malignancies common among DS subjects." (PMID 34209847, 2021).